LGALS3 (galectin 3)
Diseases named in the same sentence as LGALS3 in open-access papers (continued):
Sharing a sentence is not in itself a finding about the gene and the disease.
heart failure (continued). "In addition, it is unclear whether our findings for galectin-3, CT-proAVP and natriuretic peptides, which were obtained from a single cohort, may be generalized to other patients’ samples with more severe heart failure symptoms." (PMID 33024450, 2020). "In a recent study of three biomarkers: Galectin 3, sSt2 and GDF-15 in adult CKD patients, higher circulating concentrations of all of them were associated with higher mortality, but only elevated GDF-15 concentrations were associated with an increased incidence of heart failure." (PMID 32899694, 2020). "Therefore we aim to evaluate whether galectin-3 correlateswith arterial stiffening markers and impaired ventricular-arterial coupling indecompensated heart failure patients." (PMID 26760784, 2016). "Galectin 3 (Gal-3) and the soluble ST2 receptor (sST2r) are two new biomarkers related to inflammation and fibrosis in heart failure (HF)." (PMID 40943112, 2025). "In clinical practice, various biomarkers have been utilized for the diagnosis and prognosis assessment of heart failure, such as BNP, NT-proBNP, cTn, galectin-3, sST2, and growth differentiation factor-15." (PMID 40406620, 2025). "There are some promising novel biomarkers, such as galectin-3, ST2, FGF-21, IGFBP-7, GDF-15, and TGF-β, that provide good specificity in diagnosing diastolic dysfunction or overt heart failure in diabetic patients." (PMID 39335666, 2024). "According to the subgroup analysis, the average concentration of galectin-3 decreased the most in the group of patients with grade 3 hypertension and NYHA class III heart failure." (PMID 36673621, 2023). "Plasma Gal-3 concentration correlates well with the severity of heart failure, therefore, the Food and Drug Administration (FDA) has included Galectin-3 (Gal-3) in the list of validated cardiovascular biomarkers." (PMID 36293342, 2022). "However, reflecting these results, studies with enough statistical power such as the GHS are required, and a more detailed look and distinction on the different entities of heart failure may identify possible issues in which galectin-3 may deliver further valuable information." (PMID 34561496, 2021). "Increased galectin-3 expression has been documented in cardiovascular diseases (CVDs), such as atherosclerosis, acute ischemic stroke, acute coronary syndrome (ACS) and heart failure (HF), arterial hypertension, cardiomyopathies or atrial fibrillation (AF)." (PMID 35053194, 2021). "Studies had concluded that in the diagnosis of heart failure, because BNP is more sensitive to volume overload, galectin-3 is more sensitive to fibrosis, a combination of the two was recommended to increase diagnostic accuracy." (PMID 35141299, 2021). "In young obese people without known cardiovascular disease, galectin-3 was related with preclinical metabolic heart disease and recommended as a screening tool for individuals with elevated risk for progression to obesity-related heart failure with preserved ejection fraction." (PMID 34561496, 2021). "Testing for both sST2 and galectin-3 are considered class II recommendations for risk prediction in heart failure from the American College of Cardiology, American Heart Association, and Heart Failure Society of America Heart Failure guidelines, but are not included in ASCO or NCCN guidelines." (PMID 34362097, 2021). "In prediabetes and T2DM, systolic function was reduced with increasing galectin-3 levels independently of age, sex, traditional CVRF, comorbidities and intake of heart failure medication." (PMID 34561496, 2021). "In addition, the clinical manifestations of heart failure may be preceded many years by active fibrosis, so the presentation of high galectin-3 level may occur before manifest HF and thus may be more effective for the prevention and prediction of disease sequelae." (PMID 33248453, 2020).
heart failure (continued). "The goal of this study is to assess the impact of AF on galectin-3 plasma level in patients hospitalized for a first NSTEMI, without reduced left ventricular ejection fraction (LVEF) and signs of heart failure." (PMID 29118378, 2017). "Galectin-3 and suppression of tumorigenicity 2 (ST2) are emerging biomarkers that are not only predictive for hospitalisation and death in patients with heart failure, but also add additional prognostic value over natriuretic peptides." (PMID 26942916, 2016). "Also, galectin-3 may be predictive of raisedpulmonary pressures and could be responsible for the pathological changes in thedistal pulmonary arteries with consequent pulmonary vascular resistance andhypertension described in heart failure." (PMID 26760784, 2016). "Thus, IL-34 may have a role to play in the pathogenesis of heart failure mediated by galectin-3." (PMID 27982136, 2016). "Galectin-3 (Gal-3) and carbohydrate antigen 125 (CA125) have emerged as robust prognostic biomarkers in heart failure." (PMID 25875367, 2015). "Galectin-3 (GAL-3), a β-galactoside–binding protein, is a new clinical biomarker believed to reflect cardiac remodeling/fibrosis in patients with heart failure (HF)." (PMID 23316284, 2012). "While plasma levels of Galectin-3 are not effective in diagnosing heart failure, they have shown value in predicting short-term mortality and the likelihood of rehospitalization." (PMID 40869365, 2025). "Elevated levels of galectin-3 in the bloodstream have been correlated with heart failure (HF), negative cardiac remodeling, myocardial fibrosis, atrial fibrillation, and coronary artery disease (CAD)." (PMID 39129285, 2025). "On the other hand, iEATv and novel biomarkers (GDF15, Galectin-3, and sST2) are validated surrogates for inflammation and remodeling, but they do not replace hard endpoints, such as incident heart failure or hospitalization." (PMID 40649060, 2025). "This study aimed to evaluate the periodontal status and levels of dipeptidyl peptidase-4 (DPP-4) and galectin-3 (Gal-3) in gingival crevicular fluid (GCF) of patients with periodontitis, heart failure (HF), and diabetes, exploring their potential as biomarkers for disease association." (PMID 40429343, 2025). "A 2015 study found that elevated galectin 3 levels in hospitalized patients with heart failure confer an additional negative prognosis, but without predictive power of death." (PMID 38541144, 2024). "In our study, heart failure and coronary artery disease frequency were similar in ESUS-PAF and ESUS + PAF groups, the elevated galectin-3 levels in ESUS + PAF group may be due to adverse LA remodeling and LA fibrosis." (PMID 38892886, 2024). "Conversely, the European Society of Cardiology in Heart Failure Guidelines emphasize the fact that the current knowledge is not enough to introduce galectin-3 into clinical practice." (PMID 35410028, 2022). "In the studies conducted in pediatric patients with congenital heart diseases, galectin-3 plasma concentration was significantly higher in children presenting with heart failure signs and symptoms than in those without." (PMID 35410028, 2022). "Beside the classic marker that is CRP (which is an independent prognostic factor for adverse events in patients with heart failure) or NT-proBNP, an increased concentration of TNF- α, ST2, IL-1, IL-6, IL-8, Galectin-3 (Gal-3), and growth differentiation factor 15 (GDF15) was also observed." (PMID 35269577, 2022). "In fact, galectin-3 has proven to be predictive of morbidity and poor prognosis in many other diseases, not just heart failure." (PMID 35141299, 2021). "Nevertheless, no single blood biomarker has demonstrated superiority to predict outcomes of heart failure requiring ECLS, but galectin-3 and ST2 have been promising and may be worthwhile to study further." (PMID 33513858, 2021).
heart failure (continued). "Galectin-3 and sST2 have not yet been sufficiently studied in guiding treatment in patients with heart failure who receive pharmacotherapy, not to mention in patients with heart failure who require ECLS." (PMID 33513858, 2021). "Galectin-3 and sST2 have been used alone or concomitantly as biomarkers in several studies regarding heart failure with or without ECLS." (PMID 33513858, 2021). "Other heart failure related biomarkers which have been explored in patients who underwent ECLS include dynamic BNP, galectin-3, ST2, matrix metalloproteinase-9 (MMP-9), tissue inhibitors of metalloproteinase-1 (TIMP-1), MMP-2, osteopontin, MR-proANP, proADM, and copeptin." (PMID 33513858, 2021). "Beside its prognostic value for heart failure patients, our data from the Diast-CHF study suggest an unknown mechanism of galectin-3 in the regulation of anxiety also in humans." (PMID 33024450, 2020). "Our data further showed that galectin-3 plasma levels in patients with ischemic and nonischemic heart failure do not differ significantly." (PMID 31885743, 2019). "This study only focused on acute myocarditis and chronic fibrosis, but there have been no analyses of time-course of galectin-3 expression in myocarditis-induced heart failure in animal models." (PMID 30673749, 2019). "Collectively, current evidence does not support single use of galectin-3 to evaluate the prognosis in patients with heart failure." (PMID 30249969, 2018). "Unlike for heart failure in the acute myocardial infarction, there is less data for the role of galectin-3 as a predictor of clinical outcome." (PMID 29118378, 2017). "Unlike for heart failure in the acute myocardial infarction, there is less data for the role of galectin-3 as a predictor of unfavorable clinical outcome." (PMID 29118378, 2017). "Galectin - 3 levels were determined on 3rd to 5th hospitalization day and patients with preexisting heart failure were not included." (PMID 29118378, 2017). "Despite markedly increased plasma galectin-3 levels in patients with heart failure, their urine galectin-3 levels are not increased." (PMID 27089335, 2016). "Concentrations of galectin-3 did not seem to depend on the level of compensation or type of heart failure." (PMID 27089335, 2016). "Plasma galectin-3 is also a novel prognostic marker for mortality in chronic heart failure and its prognostic value is independent of the severity of heart failure." (PMID 27089335, 2016). "Preclinical studies in heart failure patients have highlighted the presence of a subpopulation of activated fibroblasts in failing hearts, characterized by high expression of extracellular matrix proteins, including type I and III collagen proteins, and galectin-3." (PMID 40558655, 2025). "New biomarkers gaining importance in heart failure management include mid-regional pro adrenomedullin (MR-proADM) and copeptin (stable C-terminal pro-peptide fragment of arginine vasopressin), indicating neurohormonal activation, ST2, and Galectin-3, indicating myocardial remodeling." (PMID 38248885, 2024). "Therefore, galectin-3 concentration in patients with HFPEF is higher than that in patients with heart failure without preserved ejection fraction, which confirms the microscopic mechanism from a macro perspective." (PMID 35141299, 2021). "Evidence that links Galectin-3 to pathogenesis of heart failure has not been fully elucidated." (PMID 33513858, 2021). "Galectin-3 is a biomarker of fibrosis, inflammation and oxidative stress, and its role in heart remodelling and exercise intolerance has not been conclusively proven in heart failure (HF) patients with reduced ejection fraction." (PMID 33028850, 2020). "Galectin-3 and atrial fibrillation showed an independent predictive value of composite clinical outcome of mortality, nonfatal myocardial infarction, nonfatal stroke, transient ischemic attack and/or heart failure." (PMID 29118378, 2017).
heart failure (continued). "They found galectin-3 was inversely related to renal function regardless of having heart failure." (PMID 27089335, 2016). "Also galectin-3 was shown to correlate with LVEF in cMRI in patients after myocardial infarction and to serve as a strong prognostic biomarker in chronic stages of heart failure." (PMID 28044067, 2016). "DEAL-HF trial showed that plasma galectin-3 level has a prognostic value regardless of heart failure severity, as assessed by NT-proBNP levels, and it may be potentially used in management of such patients." (PMID 25960597, 2015). "In light of the data indicating that galectin-3 does not correlate with age in healthy children, it is becoming a new, promising tool in the diagnosis of such cardiovascular system disorders as a heart failure, cardiomyopathies, inflammatory diseases, or congenital heart diseases." (PMID 35410028, 2022). "In other studies a positive correlation between serum galectin-3 concentration and a negative correlation between left ventricular ejection fraction (LVEF%) and the degree of heart failure progression (max." (PMID 35053194, 2021). "In our study, galectin-3 plasma concentration in patients with the first acute NSTEMI, without reduced LVEF and signs of heart failure, was significantly higher in the group of patients with preexisting AF, compared with the patients without AF." (PMID 29118378, 2017). "Galectin-3 plasma concentration in patients with the first acute NSTEMI, without reduced LVEF and signs of heart failure, ranged from 3.82 up to 14.10 ng/ml (mean value 9.42 ± 2.57)." (PMID 29118378, 2017). "The receiver operating characteristic curve analysis was done to determine the optimal galectin-3 concentration cut-off value for prediction of AF in patients with first acute NSTEMI, without reduced LVEF and signs of heart failure." (PMID 29118378, 2017).
diabetes (173 papers, 2007 to 2026). "This lack of association between galactin-3 and insulin resistance in the current study appears to be at variance with previous studies that associated galectin-3 with insulin signaling and incidence and prevalence of diabetes." (PMID 40802820, 2025). "Additional inclusion of galectin-3 improved the predictive power of the conventional clinical risk model including age, gender, diabetes, hypertension, diabetes, and hypercholesterolemia." (PMID 40747494, 2025). "In a previous study, serum galectin-3 level was positively associated with BMI in type 2 diabetes mellitus patients (r = 0.357, P = 0.001)." (PMID 37626284, 2023). "In the present study, we investigated for the first time the three SNP polymorphisms of the LGALS3 gene and its correlation with hemoglobin levels, rate of glomerular filtration, level of parathyroid hormone, diabetes mellitus, and arterial hypertension." (PMID 35807161, 2022). "We summarized the roles of Galectin-3 in diabetes and its complications, as well as the underlying mechanisms." (PMID 35083706, 2022). "In both groups, higher concentrations of galectin-3 were associated with older age, longer duration of diabetes, and higher UACR." (PMID 36175599, 2022). "Despite a strong association between galectin-3 concentration and renal function loss in diabetes, the exact mechanism underlying the association is controversial." (PMID 36175599, 2022). "In accordance with their finding, our results showed that patients who had LGALS3 rs4644 CC and rs4652 AA genotypes had a 3.2- and 10-times-higher risk of developing diabetes mellitus." (PMID 35807161, 2022). "Several studies in humans have reported that the elevation of serum galectin-3 levels was significantly associated with gastric cancer, renal failure, diabetes mellitus (DM), and heart failure (HF)." (PMID 34722704, 2021). "Secondly, this cross-sectional study failed to determine the causality or temporal relationship among galectin-3, adiponectin and diabetes development." (PMID 34096884, 2021). "On the other hand, galectin-3 wields multivariable and to some extent contrary functions: galectin-3 deficient mice were associated with less atherosclerosis, inflammation and diabetes mellitus after infusion of streptozotocin." (PMID 34561496, 2021). "The combination + lipids + galectin-3/adiponectin model was proved to have good discrimination and clinical efficacy, which provided a new entry point for the establishment of a diabetes risk assessment model in the future." (PMID 34096884, 2021). "The combination + lipids + galectin-3/adiponectin model displayed favorable performance in diabetes risk assessment." (PMID 34096884, 2021). "Association of increased adiponectin, galectin-3 and galectin-3/adiponectin with risk of prevalent diabetes." (PMID 34096884, 2021). "In a large, multiethnic study conducted in Dallas, galectin-3 was associated with diabetes prevalence and incidence, possibly through the inflammatory pathway contributing to B-cell fibrosis and impaired insulin secretion." (PMID 34096884, 2021). "In this study, we demonstrated that high galectin-3 and low adiponectin levels were clinically associated with type 2 diabetes, and their joint action played an outstanding role in diabetes risk assessment." (PMID 34096884, 2021). "Meanwhile, this investigation yielded novel findings with regard to the positive galectin-3/adiponectin diabetes association in an older population." (PMID 34096884, 2021). "As an instance, a recent study reported that depression in diabetes was linked to higher levels of Galectin-3." (PMID 34516574, 2021). "Galectin-3 protein encoded by lectin galactoside-binding soluble-3 (LGALS-3) gene is an important genetic factor in type 2 diabetes mellitus (T2DM) and its cardiovascular obstacles in various populations." (PMID 34616230, 2021).